RN7SL749P (RNA, 7SL, cytoplasmic 749, pseudogene)
Gene: Miscellaneous RNA gene on chromosome 10 (119,212,857 to 119,213,146, forward strand). Ensembl gene ENSG00000242853.
Homologues: Orthologues: chimpanzee Metazoa_SRP (99% identical), macaque Metazoa_SRP (90% identical). Paralogues in human: RN7SL1 (84% identical), RN7SL2 (84% identical), RN7SL3 (83% identical), RN7SL126P (81% identical), RN7SL230P (80% identical), RN7SL45P (80% identical), RN7SL464P (80% identical), RN7SL296P (80% identical), RN7SL147P (79% identical), RN7SL186P (79% identical), RN7SL493P (79% identical), RN7SL597P (79% identical), and 701 more.